MCL1 (MCL1 apoptosis regulator, BCL2 family member)
Diseases named in the same sentence as MCL1 in open-access papers (continued):
Sharing a sentence is not in itself a finding about the gene and the disease.
pulmonary hypertension (2 papers, 2025 to 2026). Increased pressure within the pulmonary circulation due to lung or heart disorder. "This dichotomy confirms MCL1’s context-dependent actions in pulmonary hypertension, warranting further research for definitive mechanistic insight." (PMID 41137320, 2025).
retinoblastoma (2 papers, 2013 to 2017). A malignant tumor that originates in the nuclear layer of the retina. "Inhibiting SYK with a small molecule inhibitor caused degradation of MCL1 and caspase mediated cell death in retinoblastoma cells in vitro and in vivo and may be a drug target for retinoblastoma." (PMID 29124525, 2017). "The upregulation of SYK found in virtually all human retinoblastomas was not evident in mouse retinoblastomas nor was upregulation of MCL1." (PMID 23765217, 2013). "Furthermore, the epigenetic landscape in mouse retinoblastoma was significantly different from human tumors and some pathways that are candidates for molecular targeted therapy for human retinoblastoma such as SYK or MCL1 are not deregulated in GEMMs." (PMID 23765217, 2013).
Richter syndrome (2 papers, 2022 to 2023). Transformation of chronic lymphocytic leukemia into aggressive non-Hodgkin's lymphoma, usually diffuse large B-cell lymphoma (immunoblastic or centroblastic variant). "Interestingly, all studies that investigated combined BCL-2 and PI3K inhibition related a major part of the synergistic activity to the diminished expression levels of the anti-apoptotic proteins MCL-1 or BCL-xL irrespective of the hematological neoplasm (DLBCL, Richter’s syndrome, NHL, and AML)." (PMID 36674872, 2023).
soft tissue sarcoma (2 papers, 2008 to 2022). A malignant neoplasm arising from muscle tissue, adipose tissue, blood vessels, fibrous tissue, or other supportive tissues excluding the bones. "Interestingly, there was only one gene with two-fold expression changes when the TRD/TRAIL cells were compared to those that were incubated with TRD alone: MCL1, that is expressed in a variety of soft tissue sarcomas and acts anti-apoptotic, was down-regulated." (PMID 19077262, 2008).
Stroke (2 papers, 2018 to 2025). Sudden impairment of blood flow to a part of the brain due to occlusion or rupture of an artery to the brain. "Stroke-associated microglial clusters showed microglia-specific dysregulation of PANoptosis regulators (MCL1, TNFRSF1A, and STAT3), with TNFRSF1A upregulated in the ischemic core." (PMID 41235394, 2025). "Four hub PANRGs (MCL1, TNFRSF1A, STAT3, Hsp90aa1) were identified, enriched in MAPK and PI3K-AKT signaling pathways and negatively associated with oxidative phosphorylation, suggesting their involvement in stroke pathogenesis." (PMID 41235394, 2025). "Validation in GSE35338 and GSE137482 showed consistent upregulation of MCL1, TNFRSF1A, and STAT3 in stroke, supporting their role as candidate biomarkers." (PMID 41235394, 2025). "Collectively, these findings suggest that MCL1, TNFRSF1A, and STAT3 regulate PANoptosis and contribute to stroke progression." (PMID 41235394, 2025).
synovial sarcoma (2 papers, 2021). "We showed that co-targeting both BCL-2 and MCL-1 proves to be an effective therapeutic approach both in cell culture and animal models of synovial sarcoma, supporting translation into clinical trials." (PMID 34065859, 2021).
systemic mastocytosis (2 papers, 2008 to 2012). Systemic mastocytosis (SM) comprises a heterogeneous group of rare acquired and chronic hematological malignancies that are related to an abnormal proliferation of mast cells in tissue, including bone marrow, with or without skin involvement. "In particular, we were interested in Mcl-1 (myeloid cell leukaemia 1) and Bim (Bcl-2 interacting mediator of cell death) in regard to their roles in survival of mast cells in vivo and systemic mastocytosis." (PMID 22438059, 2012). "In a recent study done by Aicheberger at al., they examined the expression and functional role of MCL-1 in neoplastic mast cells and tried to determine whether MCL-1 could serve as a target in systemic mastocytosis." (PMID 18789152, 2008).
thymic carcinoma (2 papers, 2021 to 2022). Thymic carcinoma (TC) is a type of thymic epithelial neoplasm characterized by a high malignant potential. "The MCL1 was a famous antiapoptotic protein and could stimulate the progression and drug resistance of thymic carcinoma." (PMID 35401932, 2022).
tongue cancer (2 papers, 2012 to 2025). A malignant neoplasm affecting the tongue. "Those hub genes involved in pathways of cancer are Bcl2, EGFR, ESR1, MMP9, PPARG, and MMP2 and those involved in PI3K-Akt signaling pathways are Bcl2, EGFR, CDK2, and MCL1 these genes are considered therapeutic targets for tongue cancer." (PMID 39863836, 2025).
abortion (1 paper, 2025). the ending of pregnancy by removing a fetus or embryo before it can survive outside the uterus. "In summary, in this study, we constructed an Nomogram prediction model for recurrent spontaneous abortion based on the expressions of MALAT1, miR-515-5p, and MCL1 mRNA, and verified its clinical application value." (PMID 41480526, 2025).
acute respiratory distress syndrome (1 paper, 2019). Progressive and life-threatening pulmonary distress in the absence of an underlying pulmonary condition, usually following major trauma or surgery. "We also evidenced that GILZ, a potent anti-inflammatory mediator implicated in cell survival, was present in human neutrophils, promoted apoptosis via Mcl-1 downregulation, and was upregulated in patients with the acute respiratory distress syndrome in relation to severity." (PMID 31419224, 2019).
adenoid cystic carcinoma (1 paper, 2022). A malignant tumor arising from the epithelial cells. "The tumorigenesis regulating gene MYB is capable of upregulating Mcl-1 in adenoid cystic carcinoma cell lines." (PMID 35524332, 2022). "Although an isolated finding, Mcl-1 amplification was observed in high-grade stage III adenoid cystic carcinoma." (PMID 35524332, 2022).
airway hyperresponsiveness (1 paper, 2020). "Whether manipulation of Mcl-1 also leads to changes in airway hyperresponsiveness or remodelling remains to be determined, but is a logical future extension of our current work." (PMID 32303624, 2020).
allergic disease (1 paper, 2020). An immune response that occurs following re-exposure to an innocuous antigen, and that requires the presence of existing antibodies against that antigen. "Together, these findings suggest that Mcl-1 may be a potential target for ameliorating allergic disease." (PMID 32303624, 2020). "We propose that manipulation of Mcl-1 could be exploited for the treatment of allergic diseases such as eosinophilic asthma in humans." (PMID 32303624, 2020).
Ascites (1 paper, 2012). Accumulation of fluid in the peritoneal cavity (between the layers of the peritoneum that lines the abdomen). "Thus, we investigated whether Mcl-1 inhibition can alter the prosurvival activity of OC ascites." (PMID 23158473, 2012).
asthma (1 paper, 2023). "The lncRNA CRNDE inhibited EMT in lung epithelial cells via the miR-29a-3p/MCL-1 axis and affected Th17/IL-17A to reduce asthma signs." (PMID 36743692, 2023). "In our study, lncRNA CRNDE inhibited EMTs in lung epithelial cells via the downregulation of the miR-29a-3p/MCL-1 axis, which resulted in Th17/IL-17A effects that reduced asthma signs." (PMID 36743692, 2023). "lncRNA CRNDE expression downregulation led to reduced inflammation and reduced lung damage in mice with induced asthma, it inhibited the EMTs of lung epithelial cells via the miR-29a-3p/MCL-1 pathway, and it reduced the levels of Th17/IL-17A cells to reduce asthma signs." (PMID 36743692, 2023).
bipolar disorder (1 paper, 2026). A disorder of the brain that causes unusual shifts in mood, energy, activity levels and the ability to carry out day-to-day tasks. "The increased levels of the anti-apoptotic/pro–cell survival markers MCL1 and BCL2 and unchanged levels of the pro–cell death markers BID and BAX suggest a balance toward activated cell survival mechanisms in the midbrains of individuals with schizophrenia and bipolar disorder." (PMID 41567988, 2026).
bone tumors (1 paper, 2023). "In bone tumors, the MSKCC cohort had significantly fewer mutations in MAP3K1, CREBBP, MCL1, GNAQ, MEF2B, MYCN, SDHA, and SMARCA4." (PMID 37546405, 2023).
brain cancer (1 paper, 2020). A primary or metastatic malignant neoplasm affecting the brain. "Interestingly, we observed that the treatment of brain cancer cells with pimozide resulted in a reduced expression of anti-apoptotic proteins Mcl-1 and Bcl-2 in U-87 MG, U-251 MG, GBM 28, and Daoy cell lines." (PMID 32971907, 2020).
carcinoma in situ (1 paper, 2017). "Recently, a few studies demonstrated that MCL1 was displayed differently in carcinoma in situ and metastatic sites, suggesting that MCL1 may participate in tumor metastasis." (PMID 28881590, 2017).
cardiac amyloidosis (1 paper, 2023). Cardiac amyloidosis is a condition whereby cardiac tissue is infiltrated by amyloid fibrils. "In addition, patients with heart disease such as cardiac amyloidosis and ischemic heart disease need to be made aware of potential myocardial damage when receiving MCL-1 inhibitors." (PMID 37880389, 2023).
childhood cancer (1 paper, 2025). "Employing predictive modeling approaches on a large set of childhood cancer cell lines with multiomics data features, we identified a potentially previously unreported cluster of CpG sites in the antiapoptotic BCL-xL/BCL2L1 gene, which predicted MCL1 inhibitor response." (PMID 39846250, 2025).
cholestasis (1 paper, 2023). Impairment of the bile flow caused by obstruction within the liver, or outside the liver in the bile duct system. "Quercetin, which affects the anti-apoptotic Mcl-1 protein, prevents liver injury following cholestasis." (PMID 37375834, 2023).
chronic periodontitis (1 paper, 2025). A chronic inflammatory process that affects the tissues that surround and support the teeth. "In addition to this, CXB downregulates anti-apoptotic proteins such as Mcl-1 and Bcl-2, further amplifying its apoptotic effects.CXB’s ability to modulate inflammatory responses can lead to enhanced apoptosis in inflamed tissues, such as those affected by chronic periodontitis associated with OSCC." (PMID 39937256, 2025).
cognitive decline (1 paper, 2020). "Following AAV-mediated delivery of an MCL-1-expressing vector into the hippocampus of these mice, we found that MCL-1 overexpression ameliorates the cognitive decline seen in the APP/PS1 mice and reduces extracellular Aβ plaque in the hippocampus." (PMID 33184293, 2020).
desmoplastic small round cell tumor (1 paper, 2015). Desmoplastic small round cell tumor (DSRCT) is an aggressive soft tissue cancer that typically arises in serous lined surfaces of the abdominal or pelvic peritoneum, and spreads to the omentum, lymph nodes and hematogenously disseminates especially to the liver. "One patient with desmoplastic small round cell tumor (DSRCT) harbored the novel AURKB and MCL1 gene amplifications." (PMID 25859559, 2015).
diabetic nephropathy (1 paper, 2023). "Together, CRD’s ability to target the miR-193b-5p/MCL-1 axis and attenuate several harmful pathways suggests it has promise as a natural therapy for diabetic kidney disease." (PMID 37833817, 2023).
Encephalopathy (1 paper, 2021). Encephalopathy is a term that means brain disease, damage, or malfunction. "Our data show that conditional deletion of anti-apoptotic Mcl-1 in neuro-glial stem cells results in a progressive encephalopathy with postnatal white matter degeneration." (PMID 34873168, 2021).
endometrial adenocarcinoma (1 paper, 2018). "In addition, endometrial adenocarcinoma patients expressed significantly higher levels of MCL-1 and lower levels of BAK and BAX, whereas BCL-xL and p21 levels did not significantly differ between the two groups." (PMID 29358688, 2018).
Erythema (1 paper, 2025). Redness of the skin, caused by hyperemia of the capillaries in the lower layers of the skin. "Other studies have also indicated that single MCL‐1 siRNA delivery or combined administration with DEXA organized chondrocyte alignment, reduced inflammatory cell infiltration and significantly alleviated symptoms such as joint swelling, erythema and soft tissue edema." (PMID 40040830, 2025).
esophageal adenocarcinoma (1 paper, 2017). A malignant tumor with glandular differentiation arising predominantly from Barrett mucosa in the lower third of the esophagus. "As expected, MCL-1 overexpression led to a reduction of CDK9 inhibitors cytotoxicity in esophageal adenocarcinoma cells." (PMID 28404924, 2017). "This conclusion is further supported by reduction of efficacy of Flavopiridol and CAN 508 in vitro with MCL-1 upregulation/overexpression in at least 2 esophageal adenocarcinoma cells." (PMID 28404924, 2017). "These along with no increase in ubiquitin mediated proteosomal degradation by pharmaceutical CDK9 inhibitors, suggest that CDK9 transcriptionally regulates MCL-1 in esophageal adenocarcinoma." (PMID 28404924, 2017). "We also studied mechanism of MCL-1 regulation by CDK9 inhibitors in esophageal adenocarcinoma." (PMID 28404924, 2017). "In summary, findings in this study demonstrate significant in vitro and in vivo efficacy of CDK9 inhibition in esophageal adenocarcinoma and identify that CDK9 regulates MCL-1 transcription by inhibiting binding of HIF-1alpha to MCL-1 promoter." (PMID 28404924, 2017). "In addition, relevance of CDK9 mediated MCL-1 regulation and mechanism by which CDK9 regulates MCL-1 is not known in esophageal adenocarcinoma, even though CDK9 mediated MCL-1 regulation is one of commonest mechanism by which CDK9 inhibitors have shown anti-tumorogenic effects in other tumors." (PMID 28404924, 2017). "In addition, role of MCL-1 in selecting patients whose tumor is more likely to respond to these CDK9 inhibitors with or without chemotherapy and radiation need to be studied in esophageal adenocarcinoma." (PMID 28404924, 2017).
Flavivirus Infections (1 paper, 2018). Infections with viruses of the genus FLAVIVIRUS, family FLAVIVIRIDAE. "In this study, we showed that flavivirus infection suppresses protein synthesis, thereby reducing the quantity of proteins with short half-lives, such as MCL1." (PMID 30261081, 2018). "Flavivirus infection attenuates cellular protein synthesis, which confers reduction of short-half-life proteins like MCL1." (PMID 30261081, 2018). "In this study, we showed that flavivirus infection suppresses expression of labile proteins such as MCL1 without observable cytotoxicity." (PMID 30261081, 2018).
follicular thyroid cancer (1 paper, 2016). "In follicular thyroid cancer cells, leptin had more dramatic effects in gene expression than those of OB3; for example leptin increased the expression of PCNA and c-Myc in FTC236 cells but decreased the expression of PCNA, c-Myc and MCL-1 in FTC238 cells." (PMID 27050378, 2016).
goiter (1 paper, 2018). Enlargement of the thyroid gland usually caused by lack of iodine in the diet, hyperthyroidism, or thyroid nodules. "In relation to MCL-1 in GD, patients with the lowest expression of this marker in lymphocytes are those with the largest goiters; those using beta-blockers also had lower expression of MCL-1 and BCL-2 in lymphocytes." (PMID 30018638, 2018). "If MCL-1 or BCL-2 is decreased in lymphocytes, they survive less and have less stimulating thyrocyte apoptosis, leading to a greater goiter volume." (PMID 30018638, 2018).
Granuloma (1 paper, 2023). A compact, organized collection of mature mononuclear phagocytes, which may be but is not necessarily accompanied by accessory features such as necrosis. "Thus, we believe that our results that specific inhibition of MCL-1 plus BCL-2 reduces M.tb growth in a human granuloma model indicate that this is a potentially promising approach for TB treatment." (PMID 37864894, 2023). "Excitingly, we found that inhibition of BCL-2 with the FDA approved ABT-199 along with MCL-1 inhibition with inhibitors in clinical trials and in the preclinical stage, significantly limits M.tb growth in human and murine macrophages, and a pre-clinical human granuloma model." (PMID 37864894, 2023). "We show that specifically inhibiting MCL-1 and BCL-2 induces apoptosis of M.tb-infected macrophages, and markedly reduces M.tb growth in human and murine macrophages, and in a pre-clinical model of human granulomas." (PMID 37864894, 2023).
Graves disease (1 paper, 2018). Graves' disease is an autoimmune disorder that leads to overactivity of the thyroid gland (hyperthyroidism).It is caused by an abnormal immune system response that causes the thyroid gland to produce too much thyroid hormones. "Therefore, the greater BID (apoptotic) expression in the thyrocytes and lower expression of MCL-1 (antiapoptotic) in lymphocytes may lead to the routine use of these drugs in therapy for Graves' disease, changing its indication." (PMID 30018638, 2018).
Helicobacter infection (1 paper, 2025). "CagA up-regulates the pro-survival factors phospho-ERK and Myeloid cell leukemia protein-1 (Mcl-1) in infected mice, interfering with host cell survival and anti-apoptotic processes that overcome epithelial self-renewal and help sustain Helicobacter infection." (PMID 40264171, 2025).
hepatic disease (1 paper, 2025). "This study aimed to demonstrate that MCL-1 is overexpressed in canine HCC compared to normal and non-neoplastic hepatic disease tissues and investigate the association between enhanced MCL-1 expression and poor prognosis in HCC dogs." (PMID 40380182, 2025). "HCC tissues exhibited significantly higher MCL-1 expression than normal canine liver tissues and tissues from non-neoplastic hepatic disease." (PMID 40380182, 2025). "Immunohistochemistry (IHC) was used to quantify MCL-1 intensity levels in normal, non-neoplastic hepatic diseases, and HCC tissues, and the differences were assessed." (PMID 40380182, 2025). "Additionally, we evaluated MCL-1 expression levels in the normal, non-neoplastic hepatic disease, and HCC tissues using immunohistochemical analysis." (PMID 40380182, 2025). "Similarly, the immunostaining scores of MCL-1 were substantially higher in canine HCC tissues than those in normal and non-neoplastic hepatic disease tissues." (PMID 40380182, 2025).
histiocytic lymphoma (1 paper, 2020). "In histiocytic lymphoma U937 cells, NDRG2 could modulate NOX5-ROS-PKR pathway-regulated Bak-to-Mcl-1 ratio to increase the sensitivity to cisplatin." (PMID 32345304, 2020).
hypopharyngeal carcinoma (1 paper, 2023). Carcinoma, predominantly squamous cell, arising from the epithelial cells of the hypopharynx. "However, only four genes have been reported to inhibit the chemosensitivity in HSCC or hypopharyngeal carcinoma, including PTGS2, PHF20, ABCC1, and MCL1." (PMID 37791141, 2023).
infertile (1 paper, 2021). "However, a recent study indicated that infertility in males could not be rescued when the sequence encoding the additional 13 a.a. in the mutant Mcl-1 protein was removed using CRISPR/Cas9." (PMID 34336857, 2021).
inflammatory breast carcinoma (1 paper, 2023). An advanced, invasive breast adenocarcinoma characterized by the presence of distinct changes in the overlying skin. "Entinostat plus MEK inhibitor pimasertib retarded cell growth in TNBC cells and inflammatory breast cancer (IBC) cells, and reduced tumor growth in mice via regulation of NOXA-participated MCL1 degradation." (PMID 36969235, 2023).